OR2T4 (olfactory receptor family 2 subfamily T member 4)
Description:
Odorant receptor.
Synonyms: OR2T4Q; OR1-60
Gene: Protein-coding gene on chromosome 1 (248,361,665 to 248,362,627, forward strand). Ensembl gene ENSG00000196944.
Subcellular location: Cell membrane
Pathways (Reactome):
Sensory Perception: Expression and translocation of olfactory receptors; Olfactory Signaling Pathway
Genetic constraint (gnomAD): Loss-of-function variants: 0 observed, 0.54 expected, observed/expected ratio (o/e) 0, 90% interval 0 to 1.83. That is too few expected variants to judge how well the gene tolerates losing a copy. Missense variants: 372 observed, 400.66 expected, observed/expected ratio (o/e) 0.93, 90% interval 0.85 to 1.01. Synonymous variants: 149 observed, 150.44 expected, observed/expected ratio (o/e) 0.99, 90% interval 0.87 to 1.13.
Homologues: Orthologues: chimpanzee OR2T4 (96% identical), dog OR2T4C (82% identical), dog OR2T4D (81% identical), dog OR2T4B (80% identical), mouse Or2t29 (78% identical), mouse Or2t48 (76% identical), rat Olr1428 (76% identical), mouse Or2t46 (76% identical), mouse Or2t49 (75% identical), dog OR2T4G (74% identical), rat Or2t47 (74% identical), mouse Or2t43 (74% identical), and 5 more. Paralogues in human: OR2T29 (89% identical), OR2T5 (89% identical), OR2T10 (69% identical), OR2T3 (64% identical), OR2T34 (63% identical), OR2T11 (62% identical), OR2T35 (61% identical), OR2T2 (61% identical), OR2T27 (60% identical), OR2T1 (59% identical), OR2T6 (56% identical), OR2M2 (53% identical), and 80 more.
Diseases named in the same sentence as OR2T4 in open-access papers:
OR2T4 is named in the same sentence as 3 diseases in open-access papers, as found by Europe PMC text mining. Sharing a sentence is not in itself a finding about the gene and the disease. The quoted sentences say what the papers report.
retinopathy (1 paper, 2024). "In GWAS analysis, we found 12 SNPs had a significant association (p < 10-4) with HCQ retinopathy in genes LCE4A, HRNR, OR2T4, NUDT17, CCDC66, PRSS3, PABPC1 and IGHV." (PMID 38548946, 2024).
OR2T4 also shares sentences with these, for which no sentence is quoted: cancer (1 paper); tumor (1).